TGFB1 (transforming growth factor beta 1)
Diseases named in the same sentence as TGFB1 in open-access papers (continued):
Sharing a sentence is not in itself a finding about the gene and the disease.
tumor (continued). "Tumor infiltrated Treg cells and M2 macrophages significantly correlate with the tumor suppressive system in STAD as they produce cytokines such as transforming growth factor beta 1 (TGF-β1), interleukin-10 (IL-10), and colony stimulating factor 1 (CSF1)." (PMID 32408477, 2020). "TGFβ1, PDGF, FGFβ and connective tissue growth factor secreted by tumour cells promote the transformation of normal fibroblasts into CAFs." (PMID 32588948, 2020). "TGFβ1 is a pleiotropic cytokine with an important role in fibrogenesis, a cofactor of cancer development and a key molecular player in the CAF-governed tumor stroma." (PMID 32899119, 2020). "Aberrant TGFβ1 signaling in UCS and other carcinomas of the breast and pancreas endow tumor cells with a selective advantage of enhanced motility and resistance to chemotherapeutics with an expansion of cancer-initiating stem-like cells." (PMID 33150300, 2020). "Stromal fibroblasts-derived chemokine CXCL12 and Transforming Growth Factor β1 (TGFβ1) induce Src-mediated EMT and proliferate tumor cells present in emboli." (PMID 33414786, 2020). "Expression of CXCR7 is enhanced during pathological inflammation and tumor development, and CXCR7 mediates TGFβ1-induced EMT48." (PMID 32439908, 2020). "We also checked TGFβ1 signal and EMT signal in primary tumours from control, hsa-miR-4756-3p inhibitor, and hsa-miR-4756-3p inhibitor + FOXM1 KO mice." (PMID 31554904, 2019). "Macrophage polarization was simulated to occur in the tumor microenvironment based on the levels of cytokines present therein, with TNF-α and TGFβ1 being representative molecules influencing M121 and M222 polarization, respectively." (PMID 31636296, 2019). "Next-generation sequencing revealed loss of heterozygosity with very high allelic frequency in NOTCH3, TGFB1, EZH2 and KMT2C in the patient tumor, the subcutaneous PDX and the PDOX." (PMID 31732509, 2019). "Other mouse xenograft models showed increased tumor dissemination and larger tumors at the site of injection when mice were injected with CCKS-1 cells and simultaneously treated with TGFβ1 as compared to vehicle control-treated mice." (PMID 31450767, 2019). "The results indicated that both TGFβ1 receptor and Smad2 were involved in the process that MSCs facilitated the expression of TGFβ1 and EGF in VX2 tumor tissue." (PMID 31528217, 2019). "Crosstalk between tumour and endothelial cells are driven by several factors including VEGF and TGFβ1, the latter being known to have a central role in GBM development." (PMID 30850588, 2019). "Transforming growth factor beta 1 promotes fibroblast cell membrane AE2 expression and HCO3- excretion, which can neutralize tumor microenvironment H+ ions to inhibit tumor cell invasion." (PMID 30971931, 2019). "Loss of heterozygosity (LOH) with very high allelic frequency was observed in NOTCH3, TGFB1, EZH2 and KMT2C in the patient tumor, the subcutaneous PDX and the PDOX." (PMID 31732509, 2019). "Strikingly, although Akt1 was not significantly different between the selected cohorts, a trend towards increased TGFβ1, CDH2 (N-cadherin) and Snail were observed in the metastatic tumor sites (N=114) compared to the tumors localized in the prostate (N=4)." (PMID 31360736, 2019). "Indeed, non-immune stromal cells in the VPr tumor expressed significantly more Tgfb1 and Tgm2 (encoding a collagen crosslinking enzyme), and scored high for a fibroblast transforming growth factor-β response signature (PMID: 29443960), which included genes related to myofibroblast function." (PMID 30824837, 2019). "Antagonizing TGFβ1 in vivo can suppress RCC tumorigenesis and regress established 786‐O tumours in athymic mice." (PMID 29239102, 2018). "Transforming growth factor beta 1 (TGFB1), secreted in the tumor micro-environment, modulates cancer growth through the specific binding to TGFBR1 and subsequent activation of intracellular signals." (PMID 30115852, 2018).
tumor (continued). "CD36 plays a role in tumor angiogenesis by binding to its ligand, thrombospondin-1 (TSP-1), and then interacting with transforming growth factor beta 1 (TGFβ1)." (PMID 29914089, 2018). "In previous studies, TGFβ1 and TNFα, either alone or in combination, have been used to experimentally induce EMT in various epithelial tumor cell types including NSCLC cells." (PMID 30356176, 2018). "Here, we used TGFβ1 and TNFα to experimentally induce EMT, increase motility, migration, and invasion of tumor cells." (PMID 30356176, 2018). "The inactivation of extracellular OPN by the OPN-R3 aptamer is able to inhibit TGFβ1-mediated MSC-to-CAF transformation and tumor growth and metastasis in a TNBC animal model." (PMID 30428522, 2018). "A previous study suggested that MSCs enhanced tumour growth but inhibited the invasiveness and metastasis of HCC by downregulating TGFβ1." (PMID 29346427, 2018). "In mechanism, transforming growth factor beta 1 (TGF-β1) mainly induces the conversion to CAFs via epithelial-mesenchymal transition (EMT), which facilitates the migration and invasion of tumor cells." (PMID 28178689, 2017). "Studies reported here show TGFβ1 induced reduction of several NK activation markers as well as reduction of endogenous NK lytic activity and NK-mediated ADCC of tumor cells." (PMID 29088859, 2017). "Therefore, on the whole, the presence of both TNFα and TGFβ1 at tumor sites, combined with the factors they induce in MSCs (as we have demonstrated), may have pro-malignancy effects that act on the TME as well as directly on the cancer cells, to promote their pro-invasive potential." (PMID 28553282, 2017). "Because diverse glucocorticoids were administered to patients, these results suggest that not only dexamethasone but also other glucocorticoids induce TGFβ1-dependent EMT and tumor progression." (PMID 28981109, 2017). "Transforming growth factor beta 1 (TGF-β1) is a cytokine that belongs to transforming growth factor beta family and have both a tumor suppressor and pro-oncogenic activity in human cancers." (PMID 28496942, 2017). "In CRCs, TGFβ1 signalling, an inducer of EMT, can be a major dysfunctional point during tumour progression." (PMID 28223538, 2017). "Moreover, inhibitor of growth, i.e. Tgfb1, Gadd45b, Igfbp6, A-kinase-anchoring protein (Akap12) and protein tyrosine phosphatase, non-receptor type substrate 1 were highly significantly repressed, from which their important role in tumor progression can be inferred." (PMID 29254206, 2017). "344SQ in hydrogels formed spheroids and secreted proangiogenic growth factors that significantly increased with exposure to transforming growth factor beta 1 (TGF-β1), a potent tumor progression-promoting factor." (PMID 27596933, 2016). "TGM2 was also reported to be upregulated in cancer cell lines by several important signaling pathways involved in tumor progression or metastasis, such as NFKB1/NF-κB, TGFB1/TGF-beta, RARA/RAR-alpha, and upon genotoxic stress." (PMID 26956429, 2016). "This study defines a previously unrecognized role of NRP-1 in regulating TGFβ1-induced EndMT and fibrosis, and advocates NRP-1 as a therapeutic target to reduce tumor fibrosis and PDAC progression." (PMID 27542226, 2016). "TGFβ1 can activate tumor promotion and the epithelial-to-mesenchymal transition (EMT), which makes tumor cells move away from their epithelial cell community and integrate into surrounding tissue." (PMID 27527140, 2016). "Upregulation of transforming growth factor beta 1 (TGFβ1), following DDR1 silencing, is thought to induce tumor cell growth arrest." (PMID 27014069, 2016). "The analysis of matched tumor cell and TAM samples from the same patients are in agreement with these conclusions with the exception of TGFB1." (PMID 27215396, 2016). "The highest tumor inhibition rate of MHCC97-H animal models was observed in the fourth week, and MHCC97-L animal models was observed in the fifth week after TGFβ-1 infectedhMSC engraftment." (PMID 26003220, 2015).
tumor (continued). "Although many genes were downregulated in GB-1 3D culture relative to the parental tumor (e.g. FGFR3, TGFβ1 and TYMP), certain genes were now upregulated (e.g. FGF2, ANGPT1 and EFNA3)." (PMID 26203665, 2015). "HBx and HCV core are the key proteins in the induction of TGFb1 signaling-dependent EMT markers, while HCV core diverts TGFb1 signaling from tumor suppression to EMT induction." (PMID 26042045, 2015). "But the highest tumor inhibition rate of MHCC97-H animal models was observed in the fourth week and MHCC97-L animal models in the fifth week after TGFβ-1 infected hMSC engraftment." (PMID 26003220, 2015). "Conditioned media (CM) of HDF treated with TGFβ1 and Fe3O4 nanoparticles (CMHDF,TGF,Fe3O4) were used to check the invasive capacity of tumor cells." (PMID 26090418, 2015). "Significantly higher TGFB1 and TGFB3 mRNA levels and lower TGFBR2 mRNA levels were observed in primary tumours compared with their paired normal tissues." (PMID 26703884, 2015). "In order to evaluate an x-fold increase in TGFβ1-triggered expression of αSMA (CMHDF, rTGFβ1; CMSCL) in comparison with mock-treatment (CMHDF), subconfluent HDF were treated with recombinant- and tumour cell-derived TGFβ1." (PMID 27919042, 2014). "Most of known Egr-1 targets are genes involved in tumor metastasis, such as plasminogen activator inhibitor-1 (PAI-1), Transforming Growth Factor-beta 1 (TGF-β1), and matrix metalloporteinase-9 (MMP-9)." (PMID 25004251, 2014). "Mice knockout for TGFβ1, TGFβRII, or SMAD4 genes are more likely to have spontaneous tumour development and excessive inflammatory responses, confirming the tumour suppressor properties of the TGF-β pathway." (PMID 24393789, 2014). "Overall, the TGFβ studies herein demonstrate that depletion of km23-1 is capable of blocking constitutive TGFβ1 production in human CRC cells, which, in turn, diminishes TGFβ's paracrine effects on cells in the tumor microenvironment." (PMID 23755307, 2013). "In the ESCC tissues, positive staining of TGFβ1 and HGF was observed in stromal fibroblasts and inflammatory cells adjacent to tumour cells, particularly at the invasive edges of tumours." (PMID 24137336, 2013). "Of those molecules a number of have been associated with cell migration/invasion, tissue remodeling and inflammatory response, processes that are likely to influence tumor cell invasion, including MCP-3 (CCL7), osteopontin, TGFB-1, IL-6 and IL-8." (PMID 23349962, 2013). "The majority of TGFβ1 and HGF expression was localised in the cytoplasm of tumour and dysplasia cells, and positive cells were distributed in the proliferative basal cell zone." (PMID 24137336, 2013). "TGFβ1 is a major node and this protein is up-regulated in diverse cancers and thought to promote invasion, migration, EMT and tumor progression." (PMID 23658826, 2013). "Other inflammation-related molecules, such as transforming growth factor β1 (TGFβ1), vascular endothelial growth factor (VEGF) and matrix metalloproteases (MMPs), become predominant during advanced tumor stages." (PMID 22848630, 2012). "M2-type macrophages from experimental tumors and various types of cancers express arginase-1 (Arg1), IL-10 and transforming growth factor beta 1 (TGF-β1), support tumor invasion, angiogenesis and matrix remodelling." (PMID 21901144, 2011). "We observed that in addition to G-CSF, the cytokine transforming growth factor β (TGFβ1) rapidly induced the expression of MAD1 mRNA and protein in promyelocytic tumor cells." (PMID 21345218, 2011). "MCF10CA1, a tumor forming cell line derived from MCF10A, has been reported to form invadopodia and undergo EMT in a process requiring PI3K and c-Src in response to TGFβ1." (PMID 19829710, 2009).
tumor (continued). "During the multistage carcinogenesis, TGFB1 may be involved in multiple important cellular processes, play a biphasic role in carcinogenesis, and inhibit proliferation of tumors in early stages of cancers, whereas it may also promote tumor growth and metastasis in later stages of cancers." (PMID 19835575, 2009). "Dendritic cells present in negative SLN appear to be more tolerogenic than those within the primary tumour because, although the median expression of ILT3 remains stable, the expression of both IDO and TGFβ1 increases (IDO 4.02, TGFβ1 2.37)." (PMID 17565341, 2007). "Transforming growth factor beta 1 (TGFB1) forms a signaling complex with transforming growth factor beta receptors 1 and 2 and has been described as both a tumor suppressor and tumor promoter." (PMID 17848193, 2007). "Immunostaining revealed that TGFβ1 was expressed in cancer cells but TGFβ3 in the stromal cells, whereas CD105 was exclusively expressed in vascular endothelial cells of tumour blood vessels." (PMID 12778073, 2003). "Conversely, downregulated genes included CD274 (PD-L1), TGFB1, and TGFBR1, which may reflect reduced transcriptional signatures of immune suppression within the tumor microenvironment." (PMID 41596590, 2026). "The VEGF pathway down-regulates VEGF expression, reduces angiogenesis, and tumor growth via the EGCG, Transforming growth factor beta 1 (TGF-β1)/mothers against decapentaplegic (SMAD), and 67-kDa laminin receptor-mediated cAMP response element-binding protein (CREB) pathways." (PMID 41608512, 2026). "In summary, our results demonstrated that BAMBIhigh DLBCL cells may tend to suppress the anti‐tumour activity of CD4 effector, regulatory, and Th1 subsets by enhancing TGFB1‐TGFBR2 signalling in the TME." (PMID 41492119, 2026). "In line with TGF-β inducing VIM-AS1 v.2 expression in several cancer cells, we found a positive and significant correlation between TGFB1 mRNA and VIM-AS1 v.2 expression in different tumor types across TCGA dataset." (PMID 41556346, 2026). "Taken together, these findings suggest that LCN2 may regulate CRC metastasis by exerting bidirectional effects on both tumor cells and TME cells, and the LCN2/TGFB1/CXCL5 axis discovered in this study represents just a fraction of its complex involvement." (PMID 40313933, 2025). "PI3K/AKT, a non-canonical Tgfβ1 pathway with known pro-proliferative effects via c-myc, has been identified to be closely related to the expansion of tumor MDSC." (PMID 41360769, 2025). "We analyzed the relationship between tumor‐infiltrating immune cells (CD4, CD8, FOXP3, CD163‐positive cells) and proteins (TGFβ1 and its downstream signal, SMAD3) expression and survival after the start of combined therapy with immune checkpoint inhibitors plus chemotherapy in SCLC." (PMID 41187938, 2025). "Notably, TGFβ1+ Tregs significantly expanded in LDCA, accumulating in late tumor grades with enhanced immunosuppressive capacity and self‐proliferation." (PMID 40891683, 2025). "The tumor-infiltrating CD8 T cells acquired an effector phenotype, evidenced by increased expression of the cytotoxic mediator granzyme B and decreased expression of the anti-inflammatory and pro-tumor cytokine TGFβ1." (PMID 40315226, 2025). "To examine this possibility, we collected a confirmed list of immunosuppressive genes and found a positive correlation between p62 and the main suppressors of T-cell immune function on the tumor cell surface, including EBAG9, PVR, B7-H3, TNFRSF14, TGFB1, and PD-L1, in most cancers." (PMID 41291343, 2025). "Tumor-adjacent s1-CAFs highly express ACTA2 and TGFB1, thereby promoting ECM remodeling and immune exclusion, while s4-CAFs, which are associated with tertiary lymphoid structures, express high levels of HLA-II molecules and chemokines, supporting anti-tumor immune responses." (PMID 41445734, 2025).
tumor (continued). "We show that SSEA‐1+ EECs play a role in endometrial tissue homeostasis and tumor suppression, and bioinformatically identify potential upstream regulators such as SPDEF and TGFB1, which may be involved in these mechanisms." (PMID 40297954, 2025). "This may be explained by SW480 being an MSS tumor that produces GM-CSF (ATCC.org), whereas HCT116 is an MSI tumor that produces immunosuppressive cytokines, such as transforming growth factor β1 (TGFβ1) and TGFβ2." (PMID 40503011, 2025). "Immunohistochemistry results showed that TGFβ1 and SMAD family member 2 (Smad2) were expressed both in cancer cells and stromal cells, including lymphocytes, plasma cells, macrophages, and fibroblasts, in the tumor microenvironment." (PMID 40899568, 2025). "Additionally, inhibiting autophagy by reducing Atg5 in tumor cells prevented EMT and metastasis formation in the context of platelet-derived TGFβ1." (PMID 40723273, 2025). "Given the decreased TGFB1 expression in exp‐CAF2‐shENG cells, we sought to determine whether the attenuated tumor‐ and metastasis‐promoting ability in these fibroblasts is due to the decreased TGF‐β1 levels." (PMID 40644310, 2025). "We then evaluated the sensitivity of WT and Tgfb1–/– 4T1 tumor–bearing mice to chemotherapy with or without PD-L1 blockade." (PMID 40590231, 2025). "CSCs form the primary tumor can favor the diffusion of pro-tumorigenic and proangiogenic factors such as VEGF-A, TGFB1, TNF-alpha and lysyl oxidase (LOX) that induce the expression of S100A (a Ca2+ binding protein involved in endothelial remodeling) in the metastatic area." (PMID 39981232, 2025). "Between ARGs_Low tumour cells and T cells, ITGB1-CD46 and ITGB1-ENG were ligand-receptor pairs with strong regulatory potential, while COL1A2, CCL3, SERPINE1, FN1 and CDKN1A were top genes target to TGFB1." (PMID 40830065, 2025). "TGFβ1 was positive in the stroma, and SMAD3 was positive in tumor cells." (PMID 41187938, 2025). "Intriguingly, we identified that TGFB1 primarily targets tumor cells rather than immune cells, potentially reflecting tumor cell origins." (PMID 40959090, 2025). "We first quantified secreted TGFβ1 levels using an ELISA assay and confirmed the significant reduction of TGFβ1 in the supernatants of ECs and pericytes isolated from sGC∆PC LLC tumors as well as in the whole-tumor lysates of sGC∆PC mice." (PMID 38528180, 2024). "When tumor cells are co-cultured with macrophages, the presence of CCA cells increases the proportion of M2-polarized TAMs and the level of transforming growth factor beta 1 (TGF-β1) secreted by TAMs, while downregulation of SHH expression reverses these increases." (PMID 39290697, 2024). "Moreover, it is possible that CCL2, CCL5, CCL18, TGFB1, and GDF15 are also produced by cells other than the VS tumor cells." (PMID 39272860, 2024). "The expressions of Nuclear factor erythroid 2-related factor 2 (Nrf2) and Transforming growth factor-beta 1 (TGFβ-1) were not altered in non-tumor cells." (PMID 38653823, 2024). "Furthermore, the clinical data of recruited CC patients showed that the serum EV-mtDNA level was positively correlated with the TGFβ1 mRNA level in NAT and that tumor tissues from patients with high levels of serum EV-mtDNA exhibited an enhanced EMT phenotype." (PMID 38688896, 2024). "Targeting TGFB1/SMAD3/RUNX1 signaling inhibits MMT-driven CAF and tumor formation in NSCLC." (PMID 39201328, 2024). "The immune escape of tumor cells can also be induced by CCL18 and TGFB1." (PMID 39272860, 2024). "Moreover, the NicheNetR analysis revealed the potential ligands expressed by C3–4 of LN tumor cells that drive exhausted signatures of CD8 TDYS in RR TFHL, including IL21, TNF, TGFB1, CD80, and CD86." (PMID 38012392, 2024).